WT1 (WT1 transcription factor)
Diseases named in the same sentence as WT1 in open-access papers (continued):
Sharing a sentence is not in itself a finding about the gene and the disease.
Wilms tumor (continued). "The present study hypothesized that WT1 and N-MYC could regulate TERT expression in Wilms tumor because both proteins have been shown to interact with the TERT promoter and both are recurrently mutated or altered in Wilms tumor." (PMID 35406427, 2022). "Because other Wilms tumor cell lines with expression of WT1 were unavailable, the NB4 acute promyelocytic leukemia cell line, which demonstrates high levels of WT1 expression, was used to validate the association between shRNA knockdown of WT1 and decreased TERT expression." (PMID 35406427, 2022). "Therefore, WT1 protein staining is unable to differentiate CPDN from Wilms tumor." (PMID 34755065, 2021). "However, in the context of WT1‐mutant Wilms tumors, this is of special importance." (PMID 29542868, 2018). "However, the increased cellular proliferation rate resulting in the formation of neoplasms with WT1 mutant genotype evident in 5–20% of Wilms' Tumor cases implicates a tumor suppressor role for WT1, indicating both proto-oncogene and tumor suppressor functions for this transcription factor." (PMID 29623275, 2018). "Furthermore, WT1 as a Wilms’ tumor gene was found to be overexpressed in various types of cancers." (PMID 29207642, 2017). "Notably, Wilms tumor, aniridia, genitourinary anomalies, and mental retardation (i.e., WAGR syndrome) are a set of conditions associated with a deletion on 11p13, which includes the WT1 gene." (PMID 28594943, 2017). "With known importance of WT1 gene in renal nephroblastoma, the different staining patterns of WT-1 in nephroblastoma and germ cell components may suggest a potential similar role of WT1 gene activation in the development of nephroblastoma in testicular germ cell tumors." (PMID 27957372, 2016). "This may not be the case for Wilms tumors with WT1 mutations, as our analyses demonstrate that the median age of onset in children with somatic WT1 mutations was 14 months." (PMID 22470196, 2012). "Wilms tumours with blastemal predominance are positive for CD56, CD57, and WT1 in the great majority of patients, although the findings must be distinguished from lymphomas, sarcomas, or less likely metastases from other regions." (PMID 40177273, 2025). "The examined markers are CD56, CD57, WT1, AMACR, KRT7, and KRTAE1/AE3, which assist to separate nephroblastoma with epithelial predominance from morphologically indistinguishable metanephric adenoma." (PMID 40177273, 2025). "A study has shown that all Wilms’ tumor samples studied have a high level of MDK, and there are two WT1 elements in the human MDK promoter region." (PMID 37240085, 2023). "The increased risks for Wilms tumor and genitourinary anomalies in WAGR patients are attributed to the deletion of WT1." (PMID 36011342, 2022). "In addition to causing ISRNS, WT1 gene mutations can also result in Denys-Drash syndrome (DDS), Frasier syndrome (FS), WAGRS, which are often accompanied by male pseudohermaphroditism, hypospadias and other urological malformations, gonadal tumors, Wilms’ tumor, and other manifestations." (PMID 35710404, 2022). "WT1 also binds to the chaperone heat shock protein 90, leading to the stabilization of WT1, and to STAT3, thus in turn leading to the increased cell proliferation of Wilms tumor cells." (PMID 35328721, 2022). "Consisting of Wilms tumor, aniridia, genitourinary abnormalities, and intellectual disability, WAGR syndrome is due to sporadic deletions of PAX6 and the contiguous WT1 (Davidoff, 2012; Szychot, Apps, & Pritchard‐Jones, 2014)." (PMID 32056389, 2020). "Large genomic rearrangements disrupting WT1 and the neighbouring PAX6 result in WAGR syndrome (Wilms’ tumour, aniridia, genito-urinary abnormalities and mental retardation)." (PMID 29181713, 2019).
Wilms tumor (continued). "Our conclusion, that NAB2 is a target gene of WT1 in leukemic cells, is consistent with data from a global genome screening, indicating that WT1 binds to the NAB2 gene in a Wilms' tumor cell line." (PMID 29152069, 2017). "A number of microarray studies have described that Wilms' tumours resemble cells from the developing kidney around the MET stage, and found a clear distinction between the WT1/β-catenin mutant and wild-type subsets of tumours." (PMID 26035382, 2015). "Synergistically overexpression of WT1 and STAT3 in tumor development, including Wilms’ tumor, increases the expression level of STAT3 target genes, including cyclin D1 and Bcl-xL, resulting in an advantage of cell proliferation." (PMID 25474318, 2014). "To investigate this, we comprehensively investigated genetic and epigenetic alterations of three loci – WT1 (11p13), WT2 (11p15.5), and CTNNB1 (3p21) — in 35 sporadic Wilms' tumours." (PMID 16909133, 2006). "Our data indicate that genetic and/or epigenetic alterations of genes at these loci, especially WT1 and WT2, is involved in the majority of Wilms' tumours, and that alterations of multiple loci occur in one-third of tumours." (PMID 16909133, 2006). "Nephroblastoma and neuroblastoma were further ruled out by negative WT1 and neurofilament staining, respectively." (PMID 40948633, 2025). "Nephroblastomas characteristically contain undifferentiated blastemal cells and typically show WT1 immunoreactivity which is absent in MPNSTs." (PMID 41179673, 2025). "Positive staining for neuroendocrine markers (NSE, synaptophysin, chromogranin A) and negative staining for lymphoid (CD3, Pax5) and nephroblastoma (WT1) markers were pivotal in confirming the tumor’s neuroendocrine origin." (PMID 40948633, 2025). "Due to the localization, the patient’s young age, the morphology of the tumour tissue, and the immunoprofile (PAX8+, TTF1+, GPC3+, PAX2+, and RCC-), adult non-anaplastic Wilms tumour with blastemal predominance was the final diagnosis (despite WT1 negativity)." (PMID 40177273, 2025). "This article also includes a literature review on published articles on WT1 negative Wilms tumour in adults and other concerns related to this topic." (PMID 40177273, 2025). "Nephroblastoma generally does not harbour mutations of BRAF but tends toward other genetic alterations, including, but not limited to WT1 and CTNNB1 mutations." (PMID 40177273, 2025). "Another study suggests that nephron progenitors, but not stromal progenitors, give rise to Wilms tumors in mouse models with β-Catenin activation or Wt1 ablation and Igf2 upregulation." (PMID 40087269, 2025). "To date, only three WT1 negative adult-type Wilms tumours have been documented in the literature (one of them reported non-specific expression)." (PMID 40177273, 2025). "Wilm's tumor, aniridia, genitourinary anomalies, and mental retardation (WAGR) syndrome is a contiguous gene deletion syndrome characterized by a denovo interstitial deletion on the p arm of chromosome 11, including the WT1 and PAX6 genes." (PMID 39600756, 2024). "And immunohistochemistry showed that vimention and CK (AE1/AE3) were positive, and Bcl‐2, CD34, CK20, SMA, and WT1 (Wilms' tumor) were negative." (PMID 38767517, 2024). "Wilms tumor can be differentiated from MA in staining as it is positive for WT1 and PAX8 and negative for vimentin and CD57." (PMID 38957819, 2024). "Nephroblastoma was never written with TSC or ADPKD, though it can also occur in the case of WT1 germline and somatic mutations." (PMID 36979978, 2023). "Genotype-phenotype correlation of constitutional WT1 pathogenic variant has also been studied in children presenting with steroid-resistant nephrotic syndrome (SRNS), with or without Wilms tumour." (PMID 34608521, 2022). "AGO1 is highly expressed in the growing lung and kidney, and its expression is significantly higher in renal tumors lacking the suppressor gene of Wilms tumor, WT1 transcription factor (WT1)." (PMID 36071981, 2022).
Wilms tumor (continued). "Still, the method is imperfect, and diagnostic pitfalls linger, seeing as specificity is lacking, with WT1 also being expressed in morphological mimics of nephroblastoma." (PMID 35453662, 2022). "As expected, none of the tumors tested showed nuclear immunostaining for WT1, except for Wilms’ tumors (three out of three cases) in both epithelial and blastemal component, in addition to a cytoplasmic immunostaining." (PMID 34943491, 2021). "In the human WT1 mutant Wilms tumor cells we did not observe a phosphorylation of this receptor in the proteome studies, although IGF2 RNA expression was high." (PMID 33379206, 2020). "It has been established that WT1‐mutant Wilms tumors do not show volume reduction after chemotherapy." (PMID 29542868, 2018). "PAN-cytokeratin and WT1, two major markers for nephroblastoma were negative as was desmin, a mesenchymal marker which can be positive in blastema-predominant nephroblastoma." (PMID 28818093, 2017). "The third case, despite the lack of WT-1 expression in the nephroblastoma component, demonstrated a common clonal origin for nephroblastoma and other germ cell tumor components in testis." (PMID 27957372, 2016). "As the patient had 46,XY gonadal dysgenesis together with renal failure (focal segmental glomerulosclerosis), and GB with dysgerminoma, without Wilm’s tumor, all pointing to FS, the WT1 gene was analyzed." (PMID 22815844, 2012). "The human EIF2C1 gene is ubiquitously expressed at low to medium levels, and EIF2C1 expression was found to be elevated in Wilms tumors that lacked functional copies of the Wilms tumor suppressor gene WT1." (PMID 20146808, 2010). "Two new chromosomal regions, 16p13.3 and 17q25, which were not previously connected to WT1 or Wilms' Tumor, are enriched for predicted WT1 targets." (PMID 18564415, 2008). "On the other hand, although WT1 mutation is not frequent, WT1 mutation and CTNNB1 (β-catenin) mutation at 3p21 are significantly correlated with Wilms' tumours." (PMID 16909133, 2006). "Only three WT1 negative adult-type Wilms tumours have been reported in the literature to this date." (PMID 40177273, 2025). "However, to postpone the possible onset of WT1-related CKD and kidney failure, it is essential to preserve as much kidney tissue as is oncologically feasible (nephron-sparing surgery) throughout the treatment course for Wilms tumor." (PMID 39698353, 2024). "Moreover, negative WT1 staining helps exclude Wilms tumor, and negative CD10 staining excludes renal cell carcinoma and urothelial carcinoma." (PMID 39429475, 2024). "Adult nephroblastoma is positive for WT1 but negative for CD57 and BRAF." (PMID 37550779, 2023). "For example, it has been suggested that WT1 testing is not indicated in isolated hypospadias without cryptorchidism, but there have been several reports of patients with such phenotype who later develop Wilms tumors." (PMID 35457073, 2022). "Interestingly, although WT1 is, without a doubt, the most sensitive and relatively specific marker for the diagnosis of Wilms’ tumor, being positive in more than 90% of cases, only ~15% of nephroblastomas manifest WT1 germline or somatic mutations." (PMID 35453662, 2022). "The WT-1 gene product is not present in all nephroblastomas and may be present in various other tumors." (PMID 28845162, 2017). "We have thus identified a Wilms tumor with a complete lack of WT1 due to a homozygous deletion." (PMID 27213811, 2016). "WT1 was identified as a gene that plays an important role in normal kidney development and inactivation of its function was shown to result in the development of Wilms’ tumors in paediatric patients." (PMID 27275197, 2015). "Other conditions associated with Wilms tumour include hemihypertrophy (WT2 gene), WAGR syndrome (Wilms tumour, aniridia, genitourinary abnormalities and mental retardation, WT1 gene), sporadic non-familial aniridia, neurofibromatosis type 1 and cerebral gigantism (Sotos syndrome)." (PMID 25889326, 2015).
Wilms tumor (continued). "Diagnosis of adult nephroblastoma could not be made because the tumor had no typical triphasic pattern morphologically and negative WT1 staining either." (PMID 25267074, 2014). "In addition, WT1 was shown to repress SALL2 promoter activity, which may provide an explanation for the upregulation of SALL2 in Wilm’s tumors resulting from WT1 inactivation." (PMID 24040083, 2013). "Interestingly, CCN3 was originally identified during MAV virus induction of nephroblastoma but is not a direct target of WT1, the Wilms tumor suppressor gene." (PMID 15361251, 2004). "These idiosyncratic cases highlight the lack of clear correlation between WT1 mutations and urogenital pathology, and intronic mutations have been reported with FS, DDS, and isolated DMS and various atypical presentations including FS with Wilms tumor and 46,XX females with FSGS only." (PMID 35211794, 2022). "Finally, GO terms related to kidney development (grey nodes) are found for the Pax8+/CreWt1co/co kidneys and the WT1-wild-type Wilms' tumours but not in the Nes-Cre Wt1co/co and WT1-mutant Wilms' tumour samples, consistent with an early, pre-MET, origin of these tumours." (PMID 26035382, 2015). "The results of current imaging studies in Wt1-Igf2 mice have confirmed the higher accuracy of T2-weighted MRI for early detection, delineation of margins, and for assessment of structural heterogeneity of Wilms tumors, as compared to T1-weghted MRI and CT with or without i.v. contrast enhancement." (PMID 22875335, 2013). "Similarly, a recent study suggests that WT1 may potentiate oncogenesis and tumor progression by transcriptionally upregulating BCL2 and that this mechanism may contribute to the heightened resistance to chemotherapy-induced apoptosis in diffuse anaplasia Wilms tumors." (PMID 40493404, 2025). "Immunohistochemical staining showed positivity for PAX8, vimentin, cytokeratin, glypican, and WT1, with focal positivity for CD57, while INI-1 was negative, which is compatible with nephroblastoma." (PMID 41393744, 2025). "In two children diagnosed with WAGR syndrome, one child (No. 31) was diagnosed with nephroblastoma via renal ultrasound examination based on the implications of a positive genetic test with a large deletion covering PAX6 and WT1." (PMID 39449022, 2024). "In contrast, neither nuclear nor cytoplasmic immunoreactivity for WT1 was observed in EWS, NB and LL, with the exception of a nuclear positivity in the blastematous and in the epithelial components of Wilms’ tumor." (PMID 34943491, 2021). "WT1, Desmin, NSE, and cytokeratin cocktail CK22 are negative in CCSK but positive in blastema-predominant Wilms′ tumor." (PMID 31676003, 2019). "In addition, Xist is imprinted in mice but not in humans and WT1 is imprinted as its alternative form, AWT1, in Wilms tumor." (PMID 30166318, 2018). "However, WT1 was negative and EWSR1 gene was identified by FISH, and therefore adult Wilms' tumor was ruled out." (PMID 22312368, 2012). "The absence of WT1 expression, lack of characteristic genetic alterations and the presence of atypical KRT7 positivity raise the question of whether this tumour represents a true nephroblastoma or a morphologically similar but biologically distinct neoplasm." (PMID 40177273, 2025).
leukemia (256 papers, 2004 to 2025). A malignant (clonal) hematologic disorder, involving hematopoietic stem cells and characterized by the presence of primitive or atypical myeloid or lymphoid cells in the bone marrow and the blood. "Although it has been shown that abnormal expression of Wilm's tumor gene 1 (WT1) is associated with the occurrence of leukemia, the specific mechanism via which it induces leukemia cells to differentiate into macrophages remains poorly understood." (PMID 40327646, 2025). "Peptide vaccines mainly target leukemia-associated antigens including nephroblastoma 1 (WT1), protease 3 (PR3), hyaluronic acid-mediated motor receptor (RHAMM), and mucin 1 (MUC1)." (PMID 40129984, 2025). "Leukemia-specific cells are specifically triggered immune cells that produce interferon gamma (IFNg), tumor necrosis factor α (TNFα) or initiate cells’ degranulation in the presence of leukemia-associated antigens (LAA) like WT1 or PRAME." (PMID 41226377, 2025). "Potentially leukemia-specific cell frequencies can be increased after stimulation of immune cells with leukemia-associated antigens (LAA) such as PRAME or WT1, respectively, with staphylococcal enterotoxin B (SEB) for healthy WB samples." (PMID 39000091, 2024). "Among the enriched genes was the tumor suppressor, WT1, whose mutations are also associated with leukemia." (PMID 39025450, 2024). "In leukemias, it has further been shown that elevated levels of WT1 are associated with a poor apoptotic response to chemotherapy." (PMID 36980278, 2023). "As an attractive tumour-associated antigen, WT1 is usually overexpressed in leukemia and various types of solid tumours." (PMID 37667197, 2023). "Initial studies have shown that most specimens of human renal carcinoma have mutations in the WT1 gene, which are closely related to the occurrence, development and prognosis of leukemia." (PMID 38028542, 2023). "Leukemia-associated antigens include Wilms’ tumor 1 (WT1) antigen, proteinase (PR)-1 and -3, preferentially expressed antigen of melanoma (PRAME) and receptor for hyaluronic acid-mediated motility (RHAMM)." (PMID 35011994, 2022). "We next sought to demonstrate AMCNP mediated immune responses against a known leukemia-associated antigen, Wilms’ tumor 1 (WT1)." (PMID 34845316, 2022). "In agreement with our findings, high expression levels of WT-1 were associated with poor prognosis of other malignancies such as leukemia and ovarian cancer." (PMID 36818371, 2022). "A decrease in the number of natural killer (NK) cells and cytotoxic T-lymphocytes (CTLs), and impaired responses to leukemia-associated antigens WT1, proteinase 3, BMI-1, and preferentially expressed antigen of melanoma (PRAME) were observed at diagnosis." (PMID 34771599, 2021). "WT1 is one of a number of leukaemia associated antigens that have been considered as promising targets for immunotherapy because of their ability to elicit specific immune responses against antigen-bearing cancerous cells while sparing normal tissues." (PMID 34262856, 2021). "Towards the end of the study treatment, patient #1 developed an increase in MRD load, for both WT1 copy number and frequency of leukaemia‐associated immunophenotype (LAIP), predicting an impending relapse." (PMID 32153780, 2020). "This study is notable in several aspects as it utilizes a healthy donor-derived TCR, genetic modification of allogeneic T cells, and provides validation of the preclinical work involved in characterizing WT1 as a leukemia-associated antigen." (PMID 33569049, 2020). "In this first‐in‐human phase I trial, TLR7/8‐matured DCs transfected with RNA encoding two leukaemia‐associated antigens (WT1 and PRAME) and CMVpp65 were used as post‐remission therapy for AML patients at high risk of relapse." (PMID 32153780, 2020).